SPON2 (spondin 2)
Description:
Cell adhesion protein that promotes adhesion and outgrowth of hippocampal embryonic neurons. Binds directly to bacteria and their components and functions as an opsonin for macrophage phagocytosis of bacteria. Essential in the initiation of the innate immune response and represents a unique pattern-recognition molecule in the ECM for microbial pathogens (By similarity). Binds bacterial lipopolysaccharide (LPS).
Synonyms: DIL-1; DIL1; M-SPONDIN; MINDIN
Tractability: Small molecule: it has a high-quality binding pocket. Antibody: UniProt places it where antibodies can reach, with medium confidence; UniProt predicts a signal peptide or a membrane-spanning region; its Gene Ontology location is reachable by antibodies, with medium confidence. PROTAC: its protein half-life has been measured.
Gene: Protein-coding gene on chromosome 4 (1,166,932 to 1,208,962, reverse strand). Ensembl gene ENSG00000159674.
Subcellular location: Secreted, extracellular space, extracellular matrix
Subcellular location (Human Protein Atlas): Vesicles; Predicted to be secreted
Pathways (Reactome):
Disease: Defective B3GALTL causes PpS
Metabolism of proteins: O-glycosylation of TSR domain-containing proteins
Gene Ontology:
Molecular function: protein binding; antigen binding; lipopolysaccharide binding
Biological process: cell adhesion
Cellular component: extracellular exosome; extracellular matrix; extracellular region
Genetic constraint (gnomAD): Loss-of-function variants: 37 observed, 31.13 expected, observed/expected ratio (o/e) 1.19, 90% interval 0.91 to 1.56. The upper end of that interval is the gene's LOEUF score, 1.56, which puts it in group 6 of 6, group 1 being the genes least tolerant of losing a copy. Missense variants: 541 observed, 447.57 expected, observed/expected ratio (o/e) 1.21, 90% interval 1.13 to 1.3. Synonymous variants: 248 observed, 208.18 expected, observed/expected ratio (o/e) 1.19, 90% interval 1.07 to 1.32.
Homologues: Orthologues: chimpanzee SPON2 (99% identical), macaque SPON2 (96% identical), rat Spon2 (86% identical), mouse Spon2 (85% identical), dog SPON2 (83% identical), pig SPON2 (83% identical), guinea pig SPON2 (81% identical), tropical clawed frog spon2 (60% identical), zebrafish spon2b (60% identical). Paralogues in human: SPON1 (31% identical), THSD7A (24% identical), THSD7B (22% identical).
Diseases named in the same sentence as SPON2 in open-access papers:
SPON2 is named in the same sentence as 91 diseases in open-access papers, as found by Europe PMC text mining. Sharing a sentence is not in itself a finding about the gene and the disease. The quoted sentences say what the papers report.
prostate carcinoma (22 papers, 2005 to 2025). A carcinoma that arises from epithelial cells of the prostate gland. "Spondin 2 (SPON2) is an extracellular matrix protein proposed as a serum biomarker for prostate cancer and implicated in cell adhesion and innate immunity." (PMID 40559998, 2025). "Hypomethylation of the promoter of SPON2 and its increased expression is associated with prostate cancer; its upregulation is also associated with colorectal cancer." (PMID 32793186, 2020). "Based on these results, we concluded that SPON2 was a new serum and histological diagnostic biomarker for prostate cancer, showing independent diagnostic value and an ability to avoid some of the problems inherent in PSA." (PMID 22615945, 2012). "Among secretory proteins implicated in prostate cancer are SPON2, MSMB and AGR2." (PMID 41200187, 2025). "In prostate cancer, SPON2 has been reported as a diagnostic biomarker that offers advances over prostate specific antigen (PSA) with improvement of diagnostic sensitivity and specificity even in cohorts with NP levels of PSA, potentially lowering false negative tests and unnecessary biopsy." (PMID 41200187, 2025). "SPON2 is considered a serum prostate cancer diagnostic biomarker." (PMID 34209090, 2021). "SPON2 has been proposed as a diagnostic biomarker for ovarian cancer and prostate cancer." (PMID 33712897, 2021). "Initially, SPON2 was reported as a diagnostic marker specific for prostate cancer." (PMID 32492954, 2020). "SPON2 has been proposed as a diagnostic biomarker of prostate cancer and ovarian cancer." (PMID 25945835, 2015). "This hypomethylated state has previously been reported to lead to SPON2 overexpression in prostate cancer and colorectal carcinoma." (PMID 40523964, 2025). "Conversely, the regulation of SPON2 by Notch has thus far been described in gastric cancer, while Notch signaling in prostate cancer is context-dependent, with both oncogenic and tumor-suppressive roles reported." (PMID 41200187, 2025). "In the prostate cancer context, recent studies have demonstrated that SPON2 can promote osteogenic responses via activation of the PI3K–AKT–mTOR pathway, supporting the biological plausibility of this signaling link in prostate tumors." (PMID 41200187, 2025). "The upregulated gene set included oncogenes such as PIK3CB, FGFRL1, and NCOA2; prostate cancer-related genes such as SPON2, PCAT4, and SCHLAP1; and cell cycle genes such as MKI67, MCM4, KIF4A, CENPF, and FLNB." (PMID 38067373, 2023). "In contrast, SPON2 is overexpressed in the serum or tissue samples of malignant tumors, such as ovarian cancer and prostate cancer." (PMID 34583750, 2021). "SPON2 has been observed to increase SPON2 gene and protein expression in liver cancer, gastric cancer, ovarian cancer, and prostate cancer." (PMID 33712897, 2021). "Dysregulation of SPON2 expression has been documented in several human cancers, including prostate cancer, gastric cancer and ovarian cancer." (PMID 34583750, 2021). "Recently, SPON2 overexpression was found in numerous tumors including hepatocellular carcinoma, colorectal cancer, gastric cancer, prostate cancer, ovarian cancer, pancreatic cancer, and pulmonary adenocarcinoma." (PMID 32952742, 2020). "Recently, it has been reported that increased spondin-2 gene and protein expression was observed in ovarian cancer, liver cancer, prostate cancer and pancreatic cancer." (PMID 28060752, 2017). "It is known that SPON2 is one kind of extracellular matrix proteins and can be secreted in some tumors, such as prostate cancer, colorectal cancer and ovarian cancer." (PMID 28938639, 2017). "As a secreted protein, serum SPON2 has been raised as a biomarker in human cancers, especially in prostate cancer and ovarian cancer." (PMID 25945835, 2015). "In prostate cancer, the mRNA of SPON2 was reduced in lymph node metastasis cancer comparing with the recurrent or nonrecurrent primary cancer." (PMID 25945835, 2015).
prostate carcinoma (continued). "Hypomethylation of SPON2 promoter lead to an upregulation of SPON2 in prostate cancer and meningioma." (PMID 25945835, 2015). "Romanuik's analysis demonstrated that SPON2 is enriched in human prostate cancer cell lines over in other human cancer cell lines." (PMID 22615945, 2012). "In addition, as early as 2013, it has been reported that SPON2 is highly expressed in prostate cancer cells, and serum SPON2 index has high sensitivity and specificity, which is suitable for tumor diagnosis." (PMID 33712897, 2021). "The eight proteins highlighted in this study (KLK3, SORD, SPON2, IMPDH2, ACTN4, ATP1B1, HSPB1, and KHDRBS1) represent a signature associated with AR modulation during the transition from androgen-dependent to castration-resistant prostate cancers." (PMID 29966326, 2018). "All evidence indicates that SPON2 is an oncogene and might be a prognostic biomarker in various cancers, such as ovarian, colorectal, prostate cancer and lung ADC." (PMID 28938639, 2017). "Increased SPON2 gene and protein expression has been observed in liver cancer, gastric cancer, ovarian cancer, pancreatic cancer, breast cancer, Barrett's adenocarcinoma and prostate cancer." (PMID 25945835, 2015). "The upregulation of SPON2 gene has been detected in liver cancer, gastric cancer, ovarian cancer, pancreatic cancer, breast cancer, Barrett's adenocarcinoma and prostate cancer." (PMID 25945835, 2015). "Therefore, although our findings highlight SPON2 as a promising biomarker, direct mechanistic studies in prostate cancer cells are needed to establish whether SPON2 engages PI3K–AKT or Notch pathways in this disease setting." (PMID 41200187, 2025). "However, recent studies have shown that SPON2 is upregulated in various carcinomas including colorectal carcinoma, hepatocellular carcinoma, laryngeal squamous cell carcinoma, and gastric cancer, as well as prostate cancer." (PMID 32492954, 2020). "This study presents an integrative strategy combining bioinformatics, transcriptomics, and experimental validation to identify SPON2 and MSMB as promising secretory biomarkers for prostate cancer." (PMID 41200187, 2025). "Despite the promising identification of SPON2 and MSMB as secreted, tumor-enriched biomarkers for prostate cancer, several limitations warrant consideration." (PMID 41200187, 2025). "The list of 10 genes again included the well-established prostate cancer markers KLK2, KLK3 (PSA), FOLH1 (PSMA), PSGR (OR51E2), STEAP2, NKX3.1 and Prostein), and also included NCAM2, SPON2 and HOXB13." (PMID 15583692, 2005). "SPON2 and MSMB are secretory, immunogenic biomarkers overexpressed in prostate cancer." (PMID 41200187, 2025). "The average concentrations of SPON2 in the plasma of healthy donors, CRC patients, CRC patients after surgery, gastric cancer (GC) patients, prostate cancer patients and benign prostatic hyperplasia patients were 8.8, 21.6, 12.7, 13.4, 7.6 and 4.5 ng/mL, respectively." (PMID 25945835, 2015).
colorectal cancer (19 papers, 2015 to 2026). A primary or metastatic malignant neoplasm that affects the colon or rectum. "This is consistent with prior studies reporting that elevated SPON2 expression is linked to tumor aggressiveness and poor prognosis in other cancer types, such as breast, gastric, and colorectal cancers." (PMID 40730813, 2025). "Metastasis-associated in colon cancer 1 (MACC1) and Spondin2 (SPON2) are newly discovered oncogenes, but little is known about their role in colorectal cancer(CRC) liver metastases." (PMID 33712897, 2021). "Previous studies showed that SPON2 expression was significantly associated with prognosis in hepatocellular carcinoma, colorectal cancer, gastric cancer, and lung adenocarcinoma." (PMID 32952742, 2020). "What is noteworthy is that, NCBI GEO gene expression database of TECs in colorectal cancer and lymphoma also verified the specific high expression of 7 out of these 12 ECM associated genes in TECs from colorectal cancer and lymphoma, i.e. SPON2, BMP-1, FN1, POSTN, THBS2, VCAN and AEBP1." (PMID 29541388, 2018). "Recent research has suggested that SPON2 mediates metastasis-associated in colon cancer 1 (MACC1)–induced colorectal cancer proliferation, invasion, and metastasis in vitro and in vivo, while aberrant overexpression of SPON2 increases adverse disease-free survival in clinical samples." (PMID 28938639, 2017). "The development and spread of colorectal cancer tumors are significantly influenced by SPON2-driven M2-TAM expansion." (PMID 37713832, 2023). "Decreased methylation within the promoter led to a corresponding increase in SPON2 expression within the cell lines, which was also detected in patients with the poorer prognosis and survival of gastric/colorectal carcinoma patients." (PMID 36611168, 2023). "Overexpression of SPON2 has been shown to promote tumor cell migration by promoting M1/M2-like Macrophage recruitment in colorectal cancer and liver cancer." (PMID 36081847, 2022). "Studies have shown that the SPON2 gene is upregulated in colorectal cancer compared to colorectal adenomas." (PMID 33712897, 2021). "In this paper, MACC1 and SPON2 were introduced to explore its mechanism of action in colorectal cancer metastasis." (PMID 33712897, 2021). "That is, the uptake characteristics of 18F-FLT can reflect the invasion and metastasis ability of colorectal cancer, and can be detected by SPON2 expression level." (PMID 33712897, 2021). "The stronger the cell's ability to metastasize, the higher its SPON2 expression, and SPON2 also reflects the metastatic ability of colorectal cancer cells." (PMID 33712897, 2021). "Overall, we uncovered a novel role for SPON2 in the regulation of macrophage polarization in colorectal cancer." (PMID 34583750, 2021). "Previous studies have shown that SPON2 plays an important role in Egr-1-mediated inhibition of proliferation, migration, and tube formation of vascular ECs in colorectal cancer." (PMID 30736838, 2019). "SPON2 and its translational product, Spondin-2, have been found to be up-regulated in many types of cancer, and its expression is a prognostic factor in prostate and colorectal cancer." (PMID 29137349, 2017). "An interesting finding was that SPON2 was upregulated in colorectal carcinoma comparing with adenoma, which was in line with previous findings." (PMID 25945835, 2015). "SPON2 (spondin-2) is an extracellular matrix glycoprotein involved with immune-modulation and cell adhesion, and has been shown to have an upregulation in a few malignancies including prostate and colorectal cancer." (PMID 41200187, 2025). "Overexpression of SPON2 has been shown to promote tumor cell migration in colorectal cancer (CRC)." (PMID 34583750, 2021). "Therefore, based on this study, the new tumor metastasis markers MACC1 and SPON2 were combined to detect the physiological function of liver metastasis of colorectal cancer." (PMID 33712897, 2021).
colorectal cancer (continued). "Initially, expression of SPON2 by MACC1 regulation was reported to promote colorectal cancer." (PMID 32492954, 2020). "In addition, SPON2 gene was upregulated in colorectal carcinoma comparing with colorectal adenoma." (PMID 25945835, 2015).
gastric cancer (16 papers, 2010 to 2025). A primary or metastatic malignant neoplasm involving the stomach. "The public database showed that SPON2 expression is associated with malignant phenotype of gastric cancer." (PMID 32492954, 2020). "Spondin-2 (SPON2) is involved in cancer progression and metastasis of many tumors; however, its role and underlying mechanism in gastric cancer are still obscure." (PMID 32492954, 2020). "Our study demonstrated that Notch signaling-mediated SPON2 upregulation is associated with aggressive progression of gastric cancer." (PMID 32492954, 2020). "Overexpression of spondin-2 in gastric cancer was significantly associated with well differentiation (P = 0.015), depth of invasion (P < 0.001), lymph node metastasis (P = 0.001), and advanced TNM stages (P = 0.004)." (PMID 28060752, 2017). "Detection the spondin-2 expression may help to identify the gastric cancer patients with high-risk factors and thus aid the selection of appropriate therapies." (PMID 28060752, 2017). "Moreover, spondin-2 overexpression was associated with poor prognosis in patients with gastric cancer in different risk groups." (PMID 28060752, 2017). "The prognostic value of spondin-2 in different subgroups based on tumor size, depth of invasion and lymph node metastasis was also estimated, which appears that spondin-2 may serve as a prognostic factor for gastric cancer patients in different risk groups." (PMID 28060752, 2017). "Therefore, it suggests that Spondin-2 may serve as a potential prognostic biomarker for gastric cancer patients in different risk groups." (PMID 28060752, 2017). "Therefore, the purpose of this study is to evaluate whether Spondin-2 expression is associated with clinicopathological parameters and prognosis of gastric cancer." (PMID 28060752, 2017). "Mechanistically, SPON2 functions in the Notch pathway in gastric cancer and inhibition of the PI3K-AKT pathway in breast cancer, thereby being located at key step points in oncogenic signaling paths." (PMID 41200187, 2025). "A series of reports have revealed that SPON2 promoted many tumors progression, including hepatocellular carcinoma, gastric cancer, and lung adenocarcinoma." (PMID 40066751, 2025). "Silencing SPON2 reduces the growth and proliferation capacity of mouse gastric cancer cells, whereas overexpression of SPON2 enhances the growth and proliferation capacity of tumor cells with increased activity." (PMID 36959811, 2023). "In conclusion, we suggest upregulated SPON2 via Notch signaling as a potential target gene to inhibit gastric cancer progression." (PMID 32492954, 2020). "In this study, we investigated the role of SPON2 and related signaling pathway in gastric cancer progression and metastasis." (PMID 32492954, 2020). "Previous reports have indicated the possibility of SPON2 as a potential target to treat gastric cancer." (PMID 32492954, 2020). "To study the role of SPON2 in gastric cancer, we confirmed SPON2 expression level in dataset of patients with gastric cancer that was publicly available on Gene Expression Omnibus (GEO) database." (PMID 32492954, 2020). "SPON2 expression levels were found to be upregulated in gastric cancer cell lines and patient tissues compared to normal gastric epithelial cells and normal controls." (PMID 32492954, 2020). "SPON2 mRNA expression was found to be significantly upregulated in tissues of patients with gastric cancer compared to healthy tissues as illustrated by GSE13861, GSE30727, GSE27342, and GSE63089 datasets." (PMID 32492954, 2020). "Our results provide new insights into the role of SPON2 as the target gene of Notch signaling in gastric cancer progression and suggest SPON2 as a potential targeting molecule in gastric cancer therapy or as a biomarker for prognosis and diagnosis." (PMID 32492954, 2020). "This is an extended evidence that Notch signaling regulates SPON2 expression to induce gastric cancer metastasis." (PMID 32492954, 2020).